DTL (denticleless E3 ubiquitin protein ligase adapter)
Diseases named in the same sentence as DTL in open-access papers (continued):
Sharing a sentence is not in itself a finding about the gene and the disease.
melanoma (10 papers, 2017 to 2025). A malignant, usually aggressive tumor composed of atypical, neoplastic melanocytes. "Overexpressed DTL has been shown to play a role in the process of malignant transformation from nevus to melanoma tissue and correlates with poor survival rates in melanoma patients." (PMID 36320118, 2022). "We also analysed cfRNA copies of KPNA2, DTL, BACE2 and DTYMK across different mutational genotypes of melanoma tissue (N = 33 BRAF/NRAS wild‐type, of those N = 4 positive for TERTprom; N = 41 BRAFV600 mutant and N = 25 NRASQ61 mutant melanomas)." (PMID 36320118, 2022). "The results showed that compared with normal nevus tissues, LINC00520, ZSCAN16-AS1, MMP9, and DTL had higher expression in melanoma, whereas XIST had lower expression." (PMID 33854593, 2021). "In recent years, research has found that DTL plays a key role in the evolution of melanoma." (PMID 41409301, 2025). "Finally, five predictive genes, ZSCAN16-AS1, LINC00520, XIST, DTL, and let-7a-5p were identified; these genes are closely related to the occurrence of melanoma." (PMID 33854593, 2021). "Its pro cancer mechanism mainly includes two aspects: on the one hand, DTL promotes the malignant progression of melanoma by reshaping the glucose metabolism process of tumor cells; On the other hand, it drives the proliferation and migration of melanoma cells via the ERK/E2F1/BUB1 signaling axis." (PMID 41409301, 2025). "Furthermore, the results of our multivariate Cox analysis suggested that the combination of DTL, LINC00520, ZSCAN16-AS1, XIST, and let-7a-5p could identify high-risk melanoma patients." (PMID 33854593, 2021). "Through a combination of bio-informatics analysis and experimental validation, we untangled the functional relevance of key genes (e.g., DTL and DERL3) in melanoma progression and stress adaptation." (PMID 41409301, 2025). "Compared to fibroblasts, prognostic genes were significantly up-regulated in 3 human melanoma cell lines, especially GPX2, DERL3, NDRG1, and DTL (p < 0.05)." (PMID 41409301, 2025). "Four of those showed reliably quantifiable cfRNA copies in plasma samples and specific expression to melanoma (KPNA2, DTL, BACE2 and DTYMK)." (PMID 36320118, 2022). "Studies have also reported that DTL is associated with poor overall survival and disease-free survival in cutaneous melanoma, and inhibition of DTL induces DNA rereplication and senescence by MLN4924 and suppresses melanoma in vitro and in vivo." (PMID 35103094, 2022). "In the current study, we found that DTL, MMP9, LINC00520, and ZSCAN16-AS1 were highly expressed in melanoma compared with normal melanocytes, whereas XIST and let-7a-5p showed the opposite trend." (PMID 33854593, 2021). "Next, plasma cfRNA samples from melanoma patients (N = 18) versus control plasma of healthy donors (N = 18) were used to determine gene expression levels of six gene candidates (KPNA2, DTL, BACE2, DTYMK, E2F3 and SLC25A13) that showed excellent diagnostic accuracy (AUC >90.0%) in tissue." (PMID 36320118, 2022). "We identified KPNA2, DTL, BACE2 and DTYMK messenger RNA (mRNA) upregulated in melanoma versus nevi tissues by unsupervised data mining (N = 175 melanoma, N = 20 normal skin, N = 6 benign nevi) and experimentally confirmed differential mRNA expression in vitro (N = 18 melanoma, N = 8 benign nevi)." (PMID 36320118, 2022). "Through the re‐analysis of single‐cell RNA‐Seq (sc‐RNA‐Seq) data derived from 31 melanoma patients, we found that KPNA2, DTL, BACE2 and DTYMK are not only expressed by melanoma cells, but also by non‐malignant cells such as endothelial cells, cancer‐associated fibroblasts (CAFs), and immune cells." (PMID 36320118, 2022). "In summary, we have identified KPNA2, DTL, BACE2 and DTYMK cfRNAs as potential pan‐tumour liquid biopsy markers for prognostic and therapy monitoring in melanoma independent of the mutational genotype." (PMID 36320118, 2022).
glioma (7 papers, 2019 to 2025). A benign or malignant brain and spinal cord tumor that arises from glial cells (astrocytes, oligodendrocytes, ependymal cells). "has been reported that circ-SHPRH encodes the protein SHPRH-146aa, which acts as a decoy, protecting the SHPRH protein from ubiquitin-mediated degradation by retinoic acid-regulated nuclear matrix-associated protein (DTL), thereby inhibiting glioma development." (PMID 41267993, 2025). "And CCNA1, DTL, and SFN were discovered as novel biomarkers for glioma diagnosis, treatment, and prognosis evaluation." (PMID 36092717, 2022). "Univariate analysis and multivariate analysis of the correlation of the expression of CDC20, UBE2C, WDR62, DTL, HOXB4 and TRIM38 with OS among glioma patients." (PMID 33914773, 2021). "Our results showed that 25 of the differentially expressed URGs were related to survival in glioma patients; six genes, CDC20, UBE3C, WDR62, DTL, HOXB4, and TRIM38, were statistically significant with an AUC value greater than 0.7." (PMID 33914773, 2021). "The genes RRM2, KIAA0101, UBE2C, LMX1A, DTL, and LBX1 demonstrated significant overexpression in all human glioma subtypes (GBM, ODG, OA, AA) with a p-value ≤ 0.0001." (PMID 31475119, 2019). "In summary, CCNA1, DTL, and SFN could serve as a new biomarker for glioma diagnosis, treatment, and prognosis evaluation." (PMID 36092717, 2022). "The remaining members of the top 10-upregulated genes, IRX5, KIAA0101, LBX1, and DTL, have been studied in other cancers, but have not been well-studied in glioma." (PMID 31475119, 2019).
colon carcinoma (6 papers, 2017 to 2022). "Moreover, in colon carcinoma, restoring miR-30a function suppressed tumor growth by targeting the 3′ UTR of denticleless protein homolog (DTL), which prove useful as an effective therapeutic strategy for colon carcinoma." (PMID 29141684, 2017).
lung carcinoma (6 papers, 2017 to 2022). "DTL expression in breast and lung cancer cell lines also showed significantly higher levels than that in the normal cells." (PMID 31409387, 2019). "Interestingly, a recent study comparing control and H2O2-treated A549 cell transcriptomes identified DTL as the second top hit regulated by the treatment and confirmed its importance in lung cancer progression." (PMID 35063803, 2022).
liver cancer (4 papers, 2020 to 2022). An epithelial or non-epithelial malignant neoplasm that arises from the liver. "This evidence suggested that the DTL gene affected the status of macrophage polarization in liver cancer." (PMID 35392073, 2022). "Studies have reported that targeting of DTL can induce cell cycle arrest and senescence and can therefore be used to treat liver cancer." (PMID 32420375, 2020). "Considering the close associations between DTL gene, DNA replication process, and tumor progression, we wanted to know whether the DTL gene played an undefined or otherwise similar role in liver cancer like other tumor types." (PMID 35392073, 2022).
cutaneous melanoma (3 papers, 2021 to 2022). A primary melanoma arising from atypical melanocytes in the skin. "In the present study, we found that overexpressed DTL was closely associated with worse survival outcomes in cutaneous melanoma patients." (PMID 35991567, 2022). "Our results revealed several novel biomarkers and biological pathways that participate in the pathogenesis of cutaneous melanoma, and demonstrated the diagnostic and prognostic value of CDC45, CENPF, DTL, FANCI, GINS2, HJURP, TPX2 and TRIP13." (PMID 33531976, 2021).
Ewing sarcoma (3 papers, 2019 to 2022). A small round cell tumor that lacks morphologic, immunohistochemical, and electron microscopic evidence of neuroectodermal differentiation. "Due to the lack of DTL-knockdown transcriptional profiles on HCC cell lines (e.g., HepG2 and Huh7), we retrospectively found that researchers knocked down DTL in other tumor cells [three Ewing’s sarcoma (ES) cell lines, (GSE20357)]." (PMID 35392073, 2022).
lung adenocarcinoma (3 papers, 2017 to 2026). A carcinoma that arises from the lung and is characterized by the presence of malignant glandular epithelial cells. "Here we infer the potential impact of 19 well-defined DCAFs in human lung adenocarcinomas (LuADCs) using integrative omics analyses, and discover that mRNA levels of DTL, DCAF4, 12 and 13 are consistently elevated whereas VBRBP is reduced in LuADCs compared to normal lung tissues." (PMID 28336923, 2017).
cervical adenocarcinoma (2 papers, 2021 to 2024). An adenocarcinoma arising from the cervical epithelium. "In addition, DTL overexpression was associated with the depth of invasion of the cervical stroma (P = 0.03112), vascular space involvement (P = 0.04297), and postoperative recurrence (P = 0.02231) among patients with cervical adenocarcinoma." (PMID 34635635, 2021). "Along with the normal group, DTL was also highly expressed in cervical adenocarcinoma tissues through the TCGA database." (PMID 34635635, 2021). "Through this study, we aimed to clarify the clinical and molecular characteristics of cervical adenocarcinoma involving overexpression of DTL and elucidate its molecular mechanism." (PMID 34635635, 2021). "Therefore, we conclude that overexpression of DTL enhanced cell motility and promoted tumor metastasis of cervical adenocarcinoma by regulating the RAC1-JNK-FOXO1 axis." (PMID 34635635, 2021). "The role of DTL in cervical adenocarcinoma was explored through in vitro and in vivo experiments." (PMID 34635635, 2021).
colorectal cancer (2 papers, 2016 to 2025). A primary or metastatic malignant neoplasm that affects the colon or rectum. "Ultimately, experimental validation through quantitative PCR in gastric and colorectal cancer tissue specimens confirmed that the transcript levels of AURKA, CEP55, DTL, and TTK are markedly elevated in tumor tissues compared to normal tissues." (PMID 40723362, 2025).
COVID-19 (2 papers, 2023 to 2025). A disease caused by infection with severe acute respiratory syndrome coronavirus 2. "In influenza, UBE2S, USP53, and TIMM10 were observed in this category, while in COVID-19, UBE2T, UBE2C, DTL, MT-ND2, UCHL1, and UBA52 were implicated." (PMID 41020849, 2025). "First, we compared the expression levels of five genes in COVID-19 and controls, finding that the expression of BIRC5, DTL, and NDC80 increased in COVID-19 while DNAJC4 and LILRB2 decreased." (PMID 37426635, 2023).
diffuse large B-cell lymphoma (2 papers, 2014 to 2023). "We also uncovered that the expression of DTL has a positive correlation with MSI in most cancers, and a negative correlation only in testicular germ cell tumors (TGCTs), thyroid carcinoma (THCA) and lymphoid neoplasm diffuse large B-cell lymphoma (DLBC)." (PMID 37038185, 2023).
endometrial cancer (2 papers, 2021 to 2025). Primary or metastatic malignant neoplasm involving the endometrium (mucous membrane that lines the endometrial cavity). "Additionally, among the genes closely associated with UBE2T expression, genes like DTL, NUF2, and MELK may also contribute to the progression of endometrial cancer." (PMID 39367897, 2025).
gastric tumor (2 papers, 2018 to 2025). "DTL has been implicated in gastric tumour growth and invasion, and in ovarian cancers." (PMID 30341281, 2018). "The violin plot showed that the expression levels of the AURKA, CEP55, DTL, and TTK genes were significantly increased in colorectal and gastric tumor tissues (p value < 0.05)." (PMID 40723362, 2025).
medulloblastoma (2 papers, 2021 to 2023). A malignant, invasive embryonal neoplasm arising from the cerebellum. "Two of these circRNAs, circular-spindle and kinetochore associated complex subunit 3 (circ-SKA3) and circ-DTL, promoted the malignant phenotype of medulloblastoma when upregulated." (PMID 36899402, 2023). "circ-SKA3 and circ-DTL promote the proliferation, migration and invasion of medulloblastoma cells by regulating the expression of host genes." (PMID 34116651, 2021). "This shows that circ-SKA3 and circ-DTL have key carcinogenic effects in the occurrence and development of medulloblastoma." (PMID 34116651, 2021). "CircRNAs have also been documented in medulloblastoma: two circRNAs (circ‐SKA3 and circ‐DTL) promoted the proliferation, migration, and invasion of medulloblastoma cells in vitro by regulating gene expression." (PMID 36899402, 2023).
thyroid carcinoma (2 papers, 2021 to 2023). "The validation of the deregulated protein expression in an independent thyroid carcinoma cohort demonstrates that miRNA-dependent oncogenes comprised in this signature, the transferrin receptor TFRC (CD71) and the E3-ubiquitin ligase DTL, are sharply upregulated in ATC." (PMID 34885022, 2021).
acute myeloid leukemia (1 paper, 2023). Acute myeloid leukemia (AML) is a group of neoplasms arising from precursor cells committed to the myeloid cell-line differentiation. "DTL was widely expressed in various cells and tissues, while it was overexpressed in tumor tissues except acute myeloid leukemia (LAML)." (PMID 37038185, 2023). "Furthermore, through analyzing the expression of DTL in normal tissues and tumor tissues from the TCGA databases, we discovered that DTL was highly expressed in tumors, except in acute myeloid leukemia (LAML)." (PMID 37038185, 2023).
adrenocortical carcinoma (1 paper, 2023). "The KM curves of OS revealed details that the overexpression of DTL was meant to poor prognosis in most tumors, such as adrenocortical carcinoma (ACC), BLCA, GBM, kidney chromophobe (KICH), KIRC, kidney renal papillary cell carcinoma (KIRP), brain lower grade glioma (LGG), and LIHC, etc.." (PMID 37038185, 2023).
breast tumors (1 paper, 2017). "Furthermore, we found that UBE2T and DTL were amplified in around 12% of breast tumors based on data contained at cBioportal." (PMID 29235520, 2017).
ductal carcinomas (1 paper, 2007). "The genes encoding proteins involved in ubiquitin-mediated proteolysis, such as USP3, RKHD2 and TTC3, and nuclear components, such as DTL, GLCC11, TTC14, FAM54A, HIST1H3B, were upregulated in ductal carcinomas." (PMID 17389037, 2007).
invasive ductal carcinoma (1 paper, 2024). "By shedding light on the interplay between CDK1 and DTL expression, our findings contribute to understanding the regulatory landscape of invasive ductal carcinoma and pave the way for future investigations and novel therapeutic avenues." (PMID 39567714, 2024).
osteosarcoma (1 paper, 2017). A usually aggressive malignant bone-forming mesenchymal neoplasm, predominantly affecting adolescents and young adults. "miR-215 inhibited expression of the DTL gene accompanied by upregulation of p21 resulting in G2-arrest, and thus drug resistance emerged in osteosarcoma." (PMID 28978183, 2017). "Another miR, miR-215, inhibited expression of denticleless protein homolog (DTL) and led to an increased resistance to methotrexate and Tomudex in osteosarcoma." (PMID 28978183, 2017).
prostate carcinoma (1 paper, 2026). A carcinoma that arises from epithelial cells of the prostate gland. "Further mechanistic studies revealed that CDC20, DTL, and RRM2 were transcriptionally regulated by the RB1/E2F1 axis, mediating cell cycle progression in prostate cancer." (PMID 41492471, 2026). "To further confirm the role of CDRs in prostate cancer cell growth, we ablated the endogenous expression of CDC20, RRM2, and DTL with cutting-edge RNA-targeted CRISPR-Cas13." (PMID 41492471, 2026).
psoriasis (1 paper, 2015). An autoimmune condition characterized by red, well-delineated plaques with silvery scales that are usually on the extensor surfaces and scalp. "Several TFs/uDBPs additionally showed altered expression in blood from psoriasis patients (increased: JUNB, STAT3, DTL, CAT; decreased: CUX2, ZNF559, AVEN, RUVBL1, RAN)." (PMID 25883770, 2015).
skin cancer (1 paper, 2023). "Although DTL has been investigated to be over-expressed in various cancers, its role in arsenic-induced skin cancer is unclear." (PMID 38133379, 2023).
stomach adenocarcinoma (1 paper, 2025). "Also, the sensitivity and specificity of the expression changes of the AURKA, CEP55, DTL, and TTK genes for distinguishing colorectal and gastric adenocarcinoma from normal tissue were evaluated by ROC analysis." (PMID 40723362, 2025).